SNRNP35 (small nuclear ribonucleoprotein U11/U12 subunit 35)
Synonyms: HM1; U1SNRNPBP; HM-1
Tractability: Small molecule: a structure with a bound ligand is known. PROTAC: UniProt records ubiquitination sites on it; ubiquitination databases record sites on it; its protein half-life has been measured.
Gene: Protein-coding gene on chromosome 12 (123,458,078 to 123,473,154, forward strand). Ensembl gene ENSG00000184209.
Subcellular location: Nucleus
Subcellular location (Human Protein Atlas): Nucleoli
Pathways (Reactome):
Metabolism of RNA: mRNA Splicing - Minor Pathway
Gene Ontology:
Molecular function: mRNA binding; snRNA binding; nucleic acid binding; RNA binding
Biological process: mRNA splicing, via spliceosome; RNA splicing; spliceosome conformational change to release U4 (or U4atac) and U1 (or U11)
Cellular component: nucleolus; nucleus; spliceosomal complex; U11/U12 snRNP; U12-type precatalytic spliceosome; U12-type spliceosomal complex; nucleoplasm; precatalytic spliceosome; ribonucleoprotein complex
Genetic constraint (gnomAD): Loss-of-function variants: 16 observed, 25.02 expected, observed/expected ratio (o/e) 0.64, 90% interval 0.43 to 0.97. The upper end of that interval is the gene's LOEUF score, 0.97, which puts it in group 4 of 6, group 1 being the genes least tolerant of losing a copy. Missense variants: 292 observed, 337.53 expected, observed/expected ratio (o/e) 0.87, 90% interval 0.79 to 0.95. Synonymous variants: 106 observed, 128.8 expected, observed/expected ratio (o/e) 0.82, 90% interval 0.7 to 0.97.
Homologues: Orthologues: chimpanzee SNRNP35 (99% identical), macaque SNRNP35 (99% identical), dog SNRNP35 (92% identical), pig SNRNP35 (91% identical), rabbit SNRNP35 (91% identical), guinea pig SNRNP35 (90% identical), mouse Snrnp35 (89% identical), rat Snrnp35 (89% identical), tropical clawed frog snrnp35 (67% identical), zebrafish snrnp35 (55% identical). Paralogues in human: SNRNP70 (40% identical).